CD1D (CD1d molecule)
Diseases named in the same sentence as CD1D in open-access papers (continued):
Sharing a sentence is not in itself a finding about the gene and the disease.
medulloblastoma (7 papers, 2019 to 2025). A malignant, invasive embryonal neoplasm arising from the cerebellum. "Among pediatric tumors, increased CD1d expression was already detected in medulloblastoma with SHH subtype, thus suggesting an immunotherapeutic option with iNKT cells." (PMID 32973759, 2020). "CD1d, CD38, and CD81 showed interesting expression profiles in the primary screen but have not been identified as markers of medulloblastoma and so they, along with CD117’s low expression in Ptch1 deleted cells, were not further investigated in this study." (PMID 30657775, 2019).
ovarian carcinoma (7 papers, 2017 to 2024). A malignant neoplasm originating from the surface ovarian epithelium. "Our previous studies on ovarian cancer demonstrated the role of the immunosuppressive lipid GD3 on CD1d-mediated NKT cell activation." (PMID 39596374, 2024). "Later studies in ovarian cancer found that GD3 is present in ovarian cancer ascites and can inhibit CD1d-mediated activation of NKT cell hybridomas." (PMID 37908366, 2023). "CD1d expressing APCs treated with GD3 significantly suppress NKT cell activation, suggesting a direct role of GD3 as a lipid antigen enriched in tumor in suppressing anti-tumor immunity in an ovarian cancer model through presentation by CD1d to NKT cells." (PMID 31620124, 2019). "When murine CD1d+ fibroblasts were treated with human ascites from ovarian cancer patients, CD1d-dependent iNKT cell activation was markedly reduced, suggesting that a soluble factor released from ovarian tumors could affect CD1d-dependent activation." (PMID 29326711, 2017). "In ovarian cancer, GD3 inhibits the NKT cell response as an immune escape mechanism via binding the CD1d antigenic-binding site." (PMID 35873547, 2022).
Allergy (6 papers, 2012 to 2022). An allergy is an immune response or reaction to substances that are usually not harmful. "Since CD1d-mediated antigen presentation contributes to various immune responses associated with infection, allergy, cancer etc., MTP inhibitors might also be useful in reducing severity of these responses." (PMID 22353470, 2012). "Cd1d1 codes for CD1d, a lipid-binding molecule on the surface of IECs and DCs that presents lipid antigens to invariant natural killer T 2 (iNKT2) cells, leading to the release of IL-4, which promotes the differentiation of Th2 cells and allergy expansion." (PMID 34684302, 2021). "As IgG and IgM antibodies against alpha-gal generated by human B cells depend on CD1d-mediated interactions between B cells and iNKT cells, there may be a role for iNKT cells and CD1d-mediated glycolipid presentation in the pathogenesis of alpha-gal allergy." (PMID 33804792, 2021).
cervical carcinoma (6 papers, 2011 to 2025). A carcinoma arising from either the exocervical squamous epithelium or the endocervical glandular epithelium. "Consistent with our finding, downregulation of CD1D has been documented in many cancer types, such as breast and cervical carcinoma, and was associated with poor survival outcomes." (PMID 37077920, 2023). "The loss of CD1d has been observed in cervical cancer lesions." (PMID 31428574, 2019). "The percentage of CD19+CD5+CD1d+ Breg cells and the level of IL-10 of patients with cervical cancer or CIN were significantly higher than those in the control group (P < 0.05)." (PMID 31316301, 2019). "In order to understand the role of Bregs in patients with cervical cancer, we analyzed CD1d+CD5+CD19+ Breg cells and the level of IL-10." (PMID 31316301, 2019). "CD1d downregulation by human papillomavirus (HPV) in infected cervical epithelial cells has been recently shown to be correlated with their progression to cervical carcinoma." (PMID 21695190, 2011). "The percentage of CD19+CD5+CD1d+ Breg lymphocytes in the PBMC of healthy controls, CIN patients, and cervical cancer patients was measured by flow cytometry." (PMID 31316301, 2019). "In human solid tumors, a correlation of downregulated CD1d expression with increasing malignancy has been reported in malignant glioma, and most recently HPV-transformed cervical carcinoma cells." (PMID 21695190, 2011). "Cell surface CD1d, a MHC-Ib molecule, is down-regulated in HPV-related lesions and in HPV-negative cervical cancer cell lines stably transfected with HPV-6 E5 and HPV-16 E5, thus linking decreased CD1d expression in the presence of HPV infection with evasion of NKT cells." (PMID 24212964, 2011). "However, downregulation of CD1d in cervical cancer lesions may not be mediated by E5, as E5 expression is often inactivated in tumor cells as a consequence of viral genome integration." (PMID 31428574, 2019).
colon carcinoma (6 papers, 2011 to 2022). "Furthermore, cancer cells can downregulate CD1d surface expression, thereby limiting direct recognition by iNKT cells, even though they have shown to kill by perforin and/or granzymes at least colon cancer cells also in a CD1d-independent manner." (PMID 35615083, 2022). "We first evaluated whether colon cancer cells expressed the CD1d molecule on their surfaces." (PMID 34535957, 2021).
glioblastoma (6 papers, 2021 to 2025). The most malignant astrocytic tumor (WHO grade IV). "In a CD1d-positive U251, orthotopic xenogenic model of glioblastoma, intracranially co-injected human type I NKT cells with α-GalCer significantly prolonged the survival of tumor-bearing mice compared with α-GalCer alone." (PMID 35163235, 2022). "In contrast, type I NKT cells failed to hinder tumor growth of CD1d-negative U87 cells in the intracranial injection model, suggesting that human type I NKT cells exert direct cytotoxicity against CD1d-expressing glioblastoma cells." (PMID 35163235, 2022). "It has been shown that the expression level of CD1d on stem-like cells derived from patient glioblastoma was lower than that on the original patient glioblastoma cells." (PMID 35163235, 2022). "Especially, because iNKT cells exhibit direct cytotoxicity against CD1d-expressing glioblastoma cells, we propose that the adoptive immunotherapy of iNKT cells should be an ideal therapeutic strategy for glioblastoma." (PMID 33128583, 2021). "To address if iNKT cells can target glioblastoma to exert anti-tumor activity, we assessed the expression of CD1d, an antigen-presenting molecule for iNKT cells, on glioblastoma cells." (PMID 33128583, 2021). "Although CD1d expression was low on glioblastoma stem-like cells, retinoic acid, which is the most common differentiating agent, upregulated CD1d expression in these cells and induced iNKT cell-mediated cytotoxicity." (PMID 33128583, 2021). "We then assessed if CD1d expression on glioblastoma stem-like cells can be upregulated to induce iNKT cell-mediated anti-tumor responses effectively." (PMID 33128583, 2021). "To further investigate if cell lines can reflect the gene expression properties of the originating patient glioblastoma tissue, we established cell lines from CD1d-positive patient glioblastoma samples." (PMID 33128583, 2021). "In conclusion, these findings suggest that CD1d expression in glioblastoma should be a critical determinant for NKT cell therapy." (PMID 33128583, 2021). "The expression level of CD1d on RA-differentiated cells was ascertained to be higher than that on the glioblastoma stem-like cells." (PMID 33128583, 2021). "We sought to determine if stem-like cells derived from glioblastoma also express CD1d to induce NKT cell-mediated anti-tumor responses." (PMID 33128583, 2021). "We performed flow cytometric analysis of surgically resected patient glioblastoma tissue and found that tumor cells from some patients expressed CD1d on the cell surface." (PMID 33128583, 2021). "The mRNA levels of the CD1D gene in RA-differentiated cells from patient glioblastoma stem-like cells were higher than the levels in patient glioblastoma stem-like cells, suggesting that CD1d expression was elevated." (PMID 33128583, 2021). "As the activation of iNKT cells is CD1d-restricted, we first examined CD1d expression in patient glioblastoma cells." (PMID 33128583, 2021). "Glioblastoma cells from 10 of 15 patients expressed CD1d, and CD1d-positive glioblastoma cells pulsed with glycolipid ligand induced iNKT cell-mediated cytotoxicity in vitro." (PMID 33128583, 2021). "Similar levels of CD1d expression were ascertained in the original patient glioblastoma tissue and patient-derived cell lines." (PMID 33128583, 2021). "On the other hand, our data demonstrated patient glioblastoma cells express CD1d on the cell surface by flow cytometry." (PMID 33128583, 2021). "In this study, we confirmed the expression of CD1d in surgically resected fresh specimens from 10 of 15 glioblastoma patients." (PMID 33128583, 2021). "In contrast, we demonstrated that iNKT cells showed therapeutic activity against CD1d-positive glioblastoma xenografts." (PMID 33128583, 2021). "Altogether, these results indicated that CD1d expression in glioblastoma triggered iNKT cell-mediated anti-tumor responses." (PMID 33128583, 2021).
glioblastoma (continued). "To address this question, we generated glioblastoma stem-like cells from patient glioblastoma and assessed CD1d expression levels by flow cytometry." (PMID 33128583, 2021). "iNKT cells were only found to be highly cytotoxic against α-GalCer-pulsed CD1d-positive glioblastoma cell line U251." (PMID 33128583, 2021). "In the current study, we found that CD1d expression on glioblastoma stem-like cells from patient tissue was increased after stimulation with all-trans RA." (PMID 33128583, 2021). "The expression level of CD1d on stem-like cells derived from patient glioblastoma was lower than that on the original patient glioblastoma cells." (PMID 33128583, 2021). "Interferon-γ (IFNγ), tumor necrosis factor-α (TNFα), granzyme B, and IL-4 levels were significantly increased in iNKT cells stimulated with the α-GalCer-pulsed glioblastoma cell lines in a CD1d-dependent manner." (PMID 33128583, 2021). "Consistent with this notion, RT-PCR was used to examine the effects of all-trans RA on CD1d expression in glioblastoma stem-like cells." (PMID 33128583, 2021). "Together, even though the extent of type I NKT infiltration in glioblastoma lesions was undetectable, the potential intracranial introduction of type I NKT cells are required against CD1d-expressing glioblastomas in tumor microenvironments abundant in endogenous glycosphingolipids." (PMID 35163235, 2022). "Interestingly, in glioblastoma stem-like cells, the expression levels of CD1d were lower than the expression levels of the CD1d-positive patient glioblastoma cells." (PMID 33128583, 2021). "Moreover, RA-differentiated cells from CD1d-positive patient glioblastoma were also sensitive to α-GalCer-dependent iNKT cell-mediated cytotoxicity." (PMID 33128583, 2021). "We propose that Natural Killer T (NKT) cells, which are unconventional T lymphocytes that recognize lipid antigens presented by CD1d molecules, may play a key immunoregulatory role in glioblastoma." (PMID 34208864, 2021). "Thus, glioblastoma cell lines from CD1d-positive patient glioblastoma samples maintain the status of CD1d expression from original patient tumor tissue, and can be used for the evaluation of iNKT cell-mediated cytotoxicity toward glioblastoma cells." (PMID 33128583, 2021). "Furthermore, the CD1d molecule in glioblastoma was functional, as CD1d-positive glioblastoma cells became highly sensitive to direct iNKT cell-mediated cytotoxicity after treatment with α-GalCer in vitro." (PMID 33128583, 2021). "Moreover, the intracranial administration of human iNKT cells led to the regression of established orthotropic human CD1d-positive glioblastoma xenografts in NOD/Shi-scid IL-2RγKO (NOG) mice." (PMID 33128583, 2021). "It is reasonable to speculate that precision medicine determined by CD1d expression in glioblastoma is required for NKT cell-based cancer immunotherapy." (PMID 33128583, 2021). "Thus, CD1d expression represents a novel target for NKT cell-based immunotherapy for glioblastoma patients." (PMID 33128583, 2021). "Therefore, CD1d expression in glioblastoma is a promising target for NKT cell-based cancer immunotherapy." (PMID 33128583, 2021). "All-trans RA induced CD1d expression on glioblastoma stem-like cells." (PMID 33128583, 2021). "However, CD1d expression was ascertained in FBS-differentiated glioblastoma cells from CD1d-positive patient glioblastoma cells." (PMID 33128583, 2021). "Moreover, intracranial administration of human iNKT cells induced tumor regression of CD1d-positive glioblastoma in orthotopic xenografts in NOD/Shi-scid IL-2RγKO (NOG) mice." (PMID 33128583, 2021). "Furthermore, CD1d-positive glioblastoma cells were sensitive to direct iNKT cell-mediated cytotoxicity with glycolipid antigens." (PMID 33128583, 2021).
glioblastoma (continued). "However, all-trans retinoic acid (RA) can induce CD1d expression in glioblastoma stem-like cells, which promotes iNKT cells to exhibit higher cytotoxicity against α-GalCer (alpha-galactosylceramide)-pulsed patient glioblastoma stem-like cells." (PMID 35163235, 2022). "Thus, CD1d expression may represent a novel target for NKT cell-based cancer immunotherapy for glioblastoma patients." (PMID 33128583, 2021). "Therefore, we examined CD1d expression in four human glioblastoma cell lines by flow cytometry." (PMID 33128583, 2021). "This led us to the hypothesis that RA may induce CD1d expression in glioblastoma stem-like cells." (PMID 33128583, 2021). "Thus, the combination of RA treatment and iNKT cell-based therapies may benefit patients with CD1d-positive glioblastoma." (PMID 33128583, 2021). "Since we excluded hematopoietic cells, which should contain CD1d-positive cell populations, by density gradient centrifugation in Lymphocyte Separation Media and CD45 staining, the CD1d-expressing cells were glioblastoma cells." (PMID 33128583, 2021). "Although the majority of solid tumors are CD1d-negative, several studies have reported the CD1d expression in malignant tumors including glioblastoma." (PMID 33128583, 2021). "We then evaluated the cytokine production of iNKT cells when stimulated with CD1d-positive and -negative human glioblastoma cells." (PMID 33128583, 2021). "In contrast, RA-differentiated cells from CD1d-negative patient glioblastoma stem-like cells had slightly higher sensitivity to α-GalCer-dependent iNKT cell-mediated cytotoxicity, though the difference was not statistically significant." (PMID 33128583, 2021). "iNKT cells exhibited higher cytotoxicity against α-GalCer-pulsed RA-differentiated cells from CD1d-positive patient glioblastoma stem-like cells than those without α-GalCer." (PMID 33128583, 2021). "Although the majority of solid tumors are CD1d negative, CD1d expression by several glioblastoma cell lines has been reported." (PMID 33128583, 2021). "Since direct cytotoxicity is one of the most important functions of activated iNKT cells, we performed an in vitro cytotoxicity assay using CD1d-positive and -negative human glioblastoma cell lines." (PMID 33128583, 2021). "RT-PCR analysis of human glioblastoma cell lines confirmed CD1d expression in both U251 and T98G cell lines but not in U87 or U138 cells, suggesting that CD1d expression in glioblastoma cells was mainly regulated at the transcriptional level." (PMID 33128583, 2021). "However, intracranial injection of ex vivo-expanded human iNKT cells showed little cytotoxicity for CD1d-negative glioblastoma cells in vivo." (PMID 33128583, 2021). "To test the hypothesis, we established RA-differentiated cells from both CD1d-positive and -negative stem-like cells of glioblastoma." (PMID 33128583, 2021).
graft versus host disease (6 papers, 2018 to 2025). An immune system disorder that occurs after allogeneic hematopoietic stem cell transplant and is a reaction of donor immune cells against host tissues. "Recent interest in using an NKT cell carrier rather than the standard T cell has gained traction, since CD1d is relatively monomorphic, has limited expression, and a reduced risk of graft-versus-host disease (GVHD)." (PMID 34072042, 2021). "Notably, no graft-versus-host disease (GvHD)-like symptoms were observed, supporting the inherent advantage of iNK T cells restricted to the monomorphic CD1d protein." (PMID 40519924, 2025).
inflammatory bowel disease (6 papers, 2014 to 2025). A spectrum of small and large bowel inflammatory diseases of unknown etiology. "Like in mouse models of inflammatory bowel disease, the pro-inflammatory switch of type II NKT cells was associated with a local overexpression of CD1d." (PMID 31191516, 2019). "In this review, we discuss the impact of iNKT cells and CD1d in the regulation of intestinal inflammation, examining both cellular and molecular factors with the potential to influence the functions of iNKT cells in inflammatory bowel diseases such as Crohn’s disease and ulcerative colitis." (PMID 38274786, 2023).
tuberculosis (6 papers, 2008 to 2022). A chronic, recurrent infection caused by the bacterium Mycobacterium tuberculosis. "These include a role for LPLA2 in surfactant degradation, catabolism of oxidized phospholipids, ocular inflammation, host response to tuberculosis, and lipid antigen presentation through CD1d." (PMID 34087196, 2021). "Similarly, several paper also reported that peripheral blood circulating Bregs with CD19+CD1d+CD5+ phenotype were increased in patients with tuberculosis." (PMID 36761174, 2022). "This information is rather important in context to the evidence that showed no direct involvement of CD1d in tuberculosis antigen presentation and to other reports suggesting non-conventional sAg presenting sites." (PMID 25649790, 2015).
COVID-19 (5 papers, 2022 to 2024). A disease caused by infection with severe acute respiratory syndrome coronavirus 2. "The evidence, therefore, did not support the hypothesis that the decrease of NKT cells in COVID-19 was related to CD1d deficiency." (PMID 35250975, 2022). "Our results revealed an increase in the level of IL-35+IL-10+ producing CD138+CD1d+ Bregs (IL-35+IL-10+ Bregs) in the blood of severe patients compared to non-hospitalized patients with COVID-19 (30% increase in the frequency of IL-35+IL-10+ Bregs, P = 0.003)." (PMID 37833265, 2023).
Glucose intolerance (5 papers, 2011 to 2014). Glucose intolerance (GI) can be defined as dysglycemia that comprises both prediabetes and diabetes. "Upon GTT, the CD1d−/− mice displayed a slower rate of glucose clearance, suggesting the development of glucose intolerance." (PMID 24465369, 2014). "However, when challenged with an intraperitoneal glucose bolus, we found that obese CD1d−/− mice demonstrated slightly worsened glucose intolerance compared to controls." (PMID 21980475, 2011).
influenza (5 papers, 2015 to 2024). An acute viral infection of the respiratory tract, occurring in isolated cases, in epidemics, or in pandemics; it is caused by serologically different strains of viruses (influenzaviruses) designated A, B, and C, has a 3-day incubation period, and usually lasts for 3 to 10 days. "The CD1d knockout mice have diminished B cell responses and reduced numbers of IL-4-secreting cells during influenza and vaccinia virus infection." (PMID 39075541, 2024). "Having shown that CD1d−/− mice have diminished B cell responses during influenza and vaccinia virus infection, we sought to determine the mechanism by which NKT cells help B cells to mount an antiviral immune response." (PMID 29249358, 2018). "Our data show that monocyte-derived DCs and inflammatory monocytes massively infiltrated the lungs during the acute phase of influenza but displayed low CD1d-based lipid-presenting capacities." (PMID 27803187, 2016). "Expression of CD1d on macrophages, but not on B cells, is required to elicit IL-4 production by iNKT cells, and mice lacking macrophages or IL-4 develop fewer germinal centers and less influenza specific IgG1 than wild-type mice." (PMID 30369933, 2018).